CXCL8 (C-X-C motif chemokine ligand 8)
Diseases named in the same sentence as CXCL8 in open-access papers (continued):
Sharing a sentence is not in itself a finding about the gene and the disease.
tumor (continued). "The chemokine CXCL8 and their chemokine receptors CXCR1/2 are also fundamental in the activation and trafficking of inflammatory mediators, and tumor progression as well as metastasis." (PMID 36226048, 2022). "Mast cells are recruited by the microenvironmental chemokines, such as CCL2, CXCL1, CXCL8/IL8, and CXCL10, to tumor tissues, and are activated by pro-inflammatory cytokines, such as stem cell facto (SCF), IL33, PGE2, leukotriene B4, and osteopontin, in there." (PMID 36211375, 2022). "The two most important cytokines, IL-6 and IL-8 (CXCL8/IL-8), are involved in various spectrum cellular pathways responsible for the proliferation, metastasis, or tumor cell survival." (PMID 35986321, 2022). "CXCR2 is not normally expressed on T cells but is specific for a variety of ligands overexpressed on a range of tumours, including CXCL1, CXCL2, CXCL5, and CXCL8." (PMID 35205725, 2022). "Cytokines CXCL1, CXCL2, and CXCL8 in Cancer Cells interact with CXCR1 and CXCR2 in Neutrophils, chemotactic the activity of Neutrophils, and promote the generation of tumor immune microenvironment." (PMID 36401283, 2022). "CXCL8 promotes the activation of matrix metalloproteinase (MMP) and enhances tumor growth and metastasis." (PMID 36164329, 2022). "Neutrophils are recruited to tumors mainly by ELR+-CXC chemokines produced by tumor cells (e.g., CXCL8, CXCL5, and CXCL6) and by neutrophils themselves (e.g., CXCL2) or by other cells of the tumor stroma." (PMID 35158948, 2022). "The increased expression of CXCL8 in HCC cells accelerates tumor proliferation, migration, and invasion and is strongly correlated with clinical stage and tumor infiltration." (PMID 36072669, 2022). "Although CXCL8 has been originally described as a proinflammatory chemokine, in the context of cancer, CXCL8 is produced by multiple cell types in the tumor microenvironment (TME), including the infiltrating immune cells, stromal cells, and the tumour cells." (PMID 35372515, 2022). "When CXCL8 activates CXCR2, neutrophils infiltrate into tumor tissue and synthesize angiogenic factors, such as VEGF, to stimulate vascularization." (PMID 36612163, 2022). "Recruitment of circulating neutrophils in tumor tissues is mainly regulated by CXCL1, CXCL2, CXCL8 and CXCL5 chemokines, the complement component anaphylatoxin C5a and tumor-derived oxysterols." (PMID 35158779, 2022). "In OSCC, P. gingivalis infection contributes to the enhanced CXCL8 and CCL2 secretion in the TME, which in turn recruits CD66b+ TANs to the site of neoplastic cells and the promotion of tumor development." (PMID 35784290, 2022). "IL-8 (CXCL8) is a pro-inflammatory chemokine that plays an essential role in inflammation and tumor progression." (PMID 35054486, 2022). "This TAM subtype also owns a high level of VEGFA, CXCL8, and IL1β, similar to previously reported TAM induced from monocyte with factor-1a stabilization in solid ovarian cancer that promoted tumor inflammation and metastasis." (PMID 35935940, 2022). "Murine orthologs of CXCL8 with functions that partially overlap with pro-tumorigenic IL-8 functions are CXCL1/KC and CXCL2/MIP2, which promote mouse tumor growth and angiogenesis." (PMID 36522309, 2022). "Exploration of the expression network indicated that inflammatory genes (CXCL8, CXCL3, PIGR, and RNASE1) and Wnt pathway genes (GAST, REG1A, TFF3, and ZG16B) are upregulated in tumor stem cells of UGICs." (PMID 35646860, 2022). "CAFs, in contrast, express paracrine molecules that promote tumour growth and therapy resistance, including growth factors (CTGF, EGF, and PDGF), chemokines (CXCL1, CXCL5, CXCL7, CXCL8, CXCL12, and CCL12), and cytokines (IL-6, IL-11, and LIF)." (PMID 36284087, 2022). "IL-1β, IL-6, CXCL8, CXCL10, and vascular endothelial growth factor comprise the M2 TAMs that contribute to cancer metastasis, immune suppression, and tumor growth." (PMID 36239108, 2022).
tumor (continued). "Senescent mesothelial cells also secreted angiogenic agents such as CXCL1, CXCL8 and VEGF to stimulate subperitoneal tumor neovascularization." (PMID 36268019, 2022). "Co-stimulation of tumor cells with CCL20 and CXCL8 decreases circ_0026344 expression and facilitates the proliferation, metastasis, and EMT of CRC." (PMID 35935996, 2022). "Interleukin-8 (IL-8 or CXCL8), a granulocyte chemokine, has multiple functions in the tumor microenvironment (TME), such as recruitment of immunosuppressive cells, promotion of tumor angiogenesis, and EMT." (PMID 35965509, 2022). "Even in reports where neutrophils have been shown to exert an anti-tumor effect, CXCL5 and CXCL8 were shown to positively correlate with neutrophil infiltration." (PMID 33603130, 2022). "In the TME, TAMs participate in tumor angiogenesis by releasing growth factors such as CCL2, CXCL8, CXCL12, EGF, IL-1β, IL-8, PIGF, TGF-β, and VEGF-A." (PMID 36105288, 2022). "IL-8, also known as CXCL8, is a proinflammatory cytokine involved in the recruitment of immune cells and tumor progression via epithelial-to-mesenchymal transition." (PMID 35927313, 2022). "Additionally, PI3K is the main intracellular downstream signal of CXCL8, PI3K causes Akt to undergo phosphorylation, and activated Akt may have a critical regulatory action in the cell survival, proliferation, angiogenesis, and metastasis of tumor cell." (PMID 35922850, 2022). "Thus, the cell-autonomous and PD-1-induced functions of PD-L1 can lead to exacerbated levels of pro-metastatic activities that are expressed by the tumor cells (proliferation and invasion) and that could affect the tumor microenvironment (CXCL8, sICAM-1, GM-CSF)." (PMID 35205789, 2022). "Knockdown of SMAD4 from human CRC cells enhances CXCL1 and CXCL8 expression and accumulates CXCR2+ neutrophils to CRC tumor." (PMID 35935996, 2022). "TIMER database analysis confirmed that CTSV and MKI67 were highly expressed in tumour tissues, while CXCL8 and PRF1 were expressed at low levels in tumour tissues, which was consistent with our findings." (PMID 35902905, 2022). "The CXCL8 mRNA levels in tumoral tissues have been correlated with CRC prognosis, poor overall survival, and tumour grade." (PMID 36433652, 2022). "It facilitates the polarization of TAMs to M2 phenotype, which can release IL6 and CXCL8 to increase the expression of TNF in CRC cells, leading to the activation of NFKB1 pathway and then promotes tumor angiogenesis and metastasis." (PMID 35186730, 2022). "Mechanistic analyses determine that CXCL8 and its receptors contribute to the survival of CRC cells, mainly by reducing the survival pressure of tumor cells and helping them become resistant to apoptosis before and after invading the blood." (PMID 35905218, 2022). "Recent investigations demonstrate several novel mechanisms of the crosstalk between CXCL8 and components in TME to facilitate tumor progression, even forming positive feedback loops." (PMID 35372515, 2022). "CXCL8, commonly known as IL-8, and its receptors CXCR1/2 are required for inflammatory cytokines activation and transportation, as well as tumor development and metastasis." (PMID 35922850, 2022). "Immature DC can be recruited to the TME by tumor-derived factors such as VEGF, HGF, b-defensin, CXCL8, and CXCL12." (PMID 36419156, 2022). "CXCL8 enhances cancer stem cell-like properties such as sphere formation, glucose uptake, SOX2, and GLUT3 expression that promote xenograft tumor growth in lung and colon cancer cells." (PMID 35011369, 2021). "Upregulation of CXCL8 stimulates the proliferation and migration of HCC cells, which is closely related to clinical stage and tumor infiltration." (PMID 34384424, 2021). "Serum CXCL8 and CXCR2 concentrations were significantly higher in GC patients than in healthy controls, similar to the well-established tumor marker (CA19-9) and marker of inflammation (CRP)." (PMID 34680333, 2021).
tumor (continued). "Tumor-produced CXCL8 attracts MDSC to the TME and elicits granulocytic MDSC to extrude NETs for nesting tumor cells." (PMID 35011369, 2021). "The AUC for CXCL8 (0.8552, p < 0.001) was higher than the AUC for its receptor CXCR2 (AUC = 0.7773, p < 0.001) and classical tumor markers (CEA—AUC = 0.5159 and CA19-9—AUC = 0.6606), and also higher than the AUC for CRP levels (AUC = 0.8488, p < 0.001)." (PMID 34680333, 2021). "An integrated gene profile and functional analysis of tumor-infiltrating immune cell (TIC) proportions revealed that DC activation markers (CD80, CD83, CD86) were positively correlated with CXCL8 expression." (PMID 34025668, 2021). "Many researchers found that selected chemokines such as CXCL8 and its specific receptor CXCR2 are involved in cancer progression via the stimulation of tumor invasion, angiogenesis and metastasis." (PMID 34680333, 2021). "The expression of chemokines such as CXCL8 and its receptor CXCR2 increase as the tumour transitions from the radial to the vertical growth phase." (PMID 34830780, 2021). "Chemokines, like CXCL2, CXCL8 and CCL5, can mobilize and activate resting NK cells, resulting in tumor cell cytolysis." (PMID 34956878, 2021). "M2 macrophages have also been reported to stimulate tumor angiogenesis via CCL-2 and CXCL8, as well as destroy the surrounding tissue matrix by producing tissue enzymes, therefore establishing a prerequisite regulation for cancer cell metastasis." (PMID 34922542, 2021). "Increased expression of CXCL8 and its receptor, CXCR2, has been correlated with tumor progression after esophagectomy." (PMID 34640631, 2021). "Tumor cell migration to metastatic lesions is promoted through MSC secretion of chemoattractants, such as CXCL1, CCL5, CXCL5, CXCL8 and CXCL7." (PMID 33472580, 2021). "Among the chemokines regulated by USP12 in tumour cells, CXCL1 and CXCL8 share the chemokine receptor CXCR2 and are strong chemoattractants that recruit TAMs and MDSCs38–40." (PMID 34381028, 2021). "TANs are typically found in the center of the tumor bulk and are attracted to the TME via macrophage migration inhibitory factor (MIF), C–X–C motif chemokine ligand 8 (CXCL8), and interleukin 8 (IL-8)." (PMID 34571905, 2021). "To further verify the results of bioinformatics analysis, we applied qRT-PCR to validate the mRNA levels of HMMR, SPP1, FN1, CCNB1, CXCL8, MAD2L1 and CCNA2 in 10 paired tumor and adjacent normal tissues with qRT-PCR." (PMID 34126961, 2021). "Chemokines secreted in tumor microenvironment (TME), as CXCL2 and CXCL8, correlate to chemoresistance." (PMID 34038868, 2021). "The results showed that TTCS was superior to NTSC in inducing the migration of tumor‐infiltrating neutrophils, and this effect was almost lost when these neutrophils were pre‐treated with CXCL6/CXCL8 and/or CXCR1 blocking antibodies." (PMID 34185422, 2021). "The role of CXCR1/2 -CXCL8 interaction with cancer has been studied from different perspectives including migration of neutrophils, TAMS, and CXCR1/2+ cancer cells to tumor sites angiogenesis, and tumor stemness." (PMID 34944943, 2021). "The M-MDSC is attracted to tumor sites by CCL2, CCL5, and CSF1 and PMN-MDSC was attracted by CXCL1, CXCL5, CXCL6, CXCL8, and CXCL12." (PMID 34858479, 2021). "In this experimental setting, the authors demonstrated that tumor-secreted CXCR1 and CXCR2 ligands, Interleukin 8 (IL-8 or CXCL-8), induce extrusion of NETs protecting tumor cells from CTL and the natural killer cell (NK) cytotoxicity." (PMID 34261496, 2021). "The result shows that in tumor cells, PMEPA1 were negatively correlated with some chemokines (including CXCL1, CXCL11, CXCL2, CXCL8, CX3CL1) and positively correlated with CXCL14 and LAG3." (PMID 34777336, 2021). "Next, we analyzed the expression of CXCL5, CXCL8, IL18RAP, and TREM2 in paired tumor and adjacent normal tissues." (PMID 33955820, 2021).
tumor (continued). "Anti-CXCL8 antibody, CXCL8 small interfering RNA, and anti-CXCL1 antibody have also been tested and such therapies have shown a reduction in tumor cell migration and angiogenesis." (PMID 33467722, 2021). "Additionally, in order to mimic BE and EAC risk factors exposure, a non-tumor esophageal cell line was incubated with oleic acid (OA) and acidified medium and/or deoxycholic acid (DCA), revealing a significant increment in LD amount as well as in COX-2 and CXCL-8 expression, and in IL-8 secretion." (PMID 33441691, 2021). "Since pre-treatment with anakinra significantly reduced the levels of chemokines (CXCL8 and CCL2) in both FaDu and UPCI-SCC90 tumour-stromal models, we reasoned that these anakinra-treated tumour-stromal models would therefore also recruit fewer leukocytes." (PMID 35047989, 2021). "NK cells which infiltrate tumour have shown proangiogenic activities, producing VEGF and IL-8/CXCL-8." (PMID 34336101, 2021). "The present paper demonstrates that among all of the proteins tested in our investigations, serum M-CSF, CXCL-8, IL-6 and TIMP-1 are better biomarkers than the currently used, well-established classical tumor marker—CEA—in the diagnosis of CRC." (PMID 34071492, 2021). "Chemokines such as CXCL8, CXCR3, CXCL1, and CXCL5 regulate the tumor immune response in tumor microenvironment." (PMID 33955820, 2021). "The different behaviors of reparixin or danirixin depend on the specific target, such as targeting CXCL8, CXCR1/CXCR2 or CXCR2, or depend on the specific target cells, such as tumor cells or different immune cell subpopulations." (PMID 34025668, 2021). "Given the relevance of the USP12-mediated chemokine, such as CXCL8, CXCL1 and CCL2, in tumour development and progression, we examined the mechanism underlying the USP12-mediated regulation." (PMID 34381028, 2021). "As expected, we also saw CXCL1, CXCL8, CXCL10, CXCL11, CXCL13, and CXCL14 in tumor tissues were upregulated in the results of TCGA data and the difference was statistically significant (p < 0.05)." (PMID 34794429, 2021). "Surprisingly, in our tumor series, miR-23a-3p expression was inversely correlated with ELK1 and CXCL8 expression and positively correlated with BMPR2 expression." (PMID 33800656, 2021). "The transmigration of neutrophils into the tumour parenchyma can occur by enhanced expression of adhesion molecules and chemokines which include CXCL1, CXCL8 and CCL15." (PMID 33917287, 2021). "For example, tumor-infiltrating MAIT and γδT cells secrete CXCL8/IL-8, a chemokine that promotes tumor cell proliferation." (PMID 34298791, 2021). "Treatment with trabectedin depleted monocytes and macrophages in several animal tumor models and resulted in reduced tumor growth, downregulation of neoangiogenesis, and production of IL-6, CCL2, and CXCL8." (PMID 33919517, 2021). "This CXCL8 upregulation via NF-κB/AP-1 mediated GBM proliferation, what suggests that there is a kind of signaling network between necrotic tissues and tumor." (PMID 32456359, 2020). "Among the chemokines, interleukin-8 (IL-8, also known as CXCL8) secreted by tumor cells potentiates tumor progression by inducing adjacent epithelial tumor cells into EMT16." (PMID 32132577, 2020). "Endothelial cell survival and tumor angiogenesis are promoted by CC chemokines: CCL2, -11, -16, and -18, as well as by proangiogenic CXC-ELR (+) chemokine CXCL8." (PMID 32456359, 2020). "Among these chemokines and cytokines, we selected CXCL8, CCL2, CXCL10, and CCL20 for further study because of their critical role in cell infiltration into the tumor microenvironment." (PMID 32971847, 2020). "Our initial studies confirmed the increased expression of CXCL8 and its two receptors CXCR1 and CXCR2 in the tumour epithelium of human CaP." (PMID 32743555, 2020).
tumor (continued). "Most pronounced among the neutrophil-recruiting/-activating chemokines produced by tumor cells and structural cells in the TME are CXCL5 (also known as epithelial neutrophil-activating peptide-78; ENA-78) and CXCL8 (interleukin-8; IL-8)." (PMID 32244751, 2020). "IL-8 (CXCL8) is known as a chemotactic factor for T cells, neutrophils and basophils and has paradoxically both tumor-promoting and -inhibitory functions." (PMID 32244723, 2020). "Mast cells produce TGF-β, CXCL8, and TNF-α, promoting epithelial-to-mesenchymal transition in tumor invasion and metastasis." (PMID 32023940, 2020). "Tumor microenvironment autophagy in endothelial and stromal cells influences disease progression and response to treatment since it supports tumor progression through the secretion of mitogenic cytokines, such as interleukin-6 (IL6) and interleukin-8 (CXCL8)." (PMID 33604297, 2020). "TCSCs recruit the neutrophils by releasing CXCL-8/IL8 and upregulate their proinflammatory roles, thus promoting tumor progression." (PMID 32982967, 2020). "The attracted neutrophils expressed CXCL1 and CXCL8, MMP-2 and MMP-9, thereby inducing tumor angiogenesis and subsequent tumor progression and metastasis." (PMID 32422991, 2020). "In order to determine the mechanism of neutrophils recruitment into the tumour, we screened neutrophil attracting chemokines (CXCL1, CXCL2, CXCL3, CXCL5, CXCL8 and CXCL12)." (PMID 32778818, 2020). "CXCL8 and CXCL1 belong to the CXC chemokine family, which acts as an important multifunctional cytokine to modulate tumour proliferation, invasion and migration in an autocrine or paracrine manner." (PMID 32730361, 2020). "CXCL8 is the most widely studied CXCR2 ligand and studies have shown that blocking this signaling axis can lead to TNBC tumor cell death and a downregulation of IL8 by proteosome inhibition." (PMID 33374595, 2020). "In fact, in vitro data showed that CXCL8, through an auto-paracrine circuit, binds CXCR1 receptor and induces the tumor sphere formation, typical of CSCs." (PMID 32982967, 2020). "The binding of CXCL8 to its receptor, CXCR1, is responsible for the formation of thyrospheres, self-renewal, and tumor-initiating ability." (PMID 32982967, 2020). "Despite an increasing number of investigations outlining the multifunctional role of CXCL-8 in CRC progression, our study is the first to evaluate the significance of CXCL-8 as a potential biomarker of CRC in comparison to the classical tumor marker." (PMID 32192002, 2020). "In a study addressing not only TNFα but also IL-1β, the two cytokines were shown to increase tumor cell proliferation in a metastasis-suppressed model of a TNBC cell line and in combination with IL-6 and CXCL8 also of luminal-A cells." (PMID 33585241, 2020). "Finally, we investigated whether overexpression of CXCL8 regulates the expression of tumor-related genes, the data from Western blotting indicated that CXCL8-overexpression cells presented significantly increased levels of ERK, p-ERK and survivin compared with their control cells." (PMID 32766720, 2020). "TAMs can synthesize chemokine ligand 5 (CCL5), chemokine ligand 8 (CXCL8), and selectively synthesize CCL18, CXCL2 and CXCL3, all of which can attract monocytes/macrophages and promote tumor progression." (PMID 32774171, 2020). "In turn, CXCL8 inhibited CD8+ T cell functions by inducing the expression of PD-L1 on macrophages, which eventually promoted tumor progression." (PMID 31892854, 2020). "MDSCs also support tumor angiogenesis by producing angiogenic factors such as VEGF, platelet-derived growth factor (PDGF), transforming growth factor beta, CXCL8, and matrix metalloproteinases (MMPs) such as MMP-2 and MMP-9." (PMID 31991604, 2020). "The expression of CXCL1, CXCL2, CXCL5, and CXCL8, which are CXCR2 ligands, and the expression of KITL and GM-CSF are strongly enhanced by KRAS signaling in cancer cells and tumor-derived hypoxia." (PMID 31474975, 2019).